DEFB128 (defensin beta 128)
Description:
Has antibacterial activity.
Synonyms: DEFB-28; DEFB28; hBD-28
Tractability: Antibody: UniProt places it where antibodies can reach, with high confidence; UniProt predicts a signal peptide or a membrane-spanning region; its Gene Ontology location is reachable by antibodies, with medium confidence.
Gene: Protein-coding gene on chromosome 20 (187,853 to 189,711, reverse strand). Ensembl gene ENSG00000185982.
Subcellular location: Secreted
Pathways (Reactome):
Immune System: Beta defensins; Defensins
Gene Ontology:
Molecular function: protein binding
Biological process: defense response to Gram-negative bacterium; defense response to Gram-positive bacterium; killing of cells of another organism; innate immune response
Cellular component: extracellular region
Genetic constraint (gnomAD): Loss-of-function variants: 1 observed, 2.58 expected, observed/expected ratio (o/e) 0.39, 90% interval 0.13 to 1.6. That is too few expected variants to judge how well the gene tolerates losing a copy. Missense variants: 129 observed, 110.84 expected, observed/expected ratio (o/e) 1.16, 90% interval 1.01 to 1.35. Synonymous variants: 59 observed, 41.44 expected, observed/expected ratio (o/e) 1.42, 90% interval 1.15 to 1.76.
Homologues: Orthologues: macaque DEFB128 (88% identical), dog DEFB128 (56% identical), pig DEFB128 (56% identical), rabbit DEFB128 (56% identical), mouse Defb20 (51% identical), guinea pig Defb128 (47% identical), rat Defb20 (47% identical). Paralogues in human: DEFB127 (31% identical), DEFB118 (30% identical), DEFB121 (26% identical), DEFB132 (26% identical), DEFB124 (24% identical), DEFB135 (24% identical), DEFB115 (23% identical), DEFB129 (23% identical), DEFB123 (20% identical), DEFB134 (20% identical), DEFB116 (19% identical), DEFB119 (19% identical), and 7 more.
Diseases named in the same sentence as DEFB128 in open-access papers:
DEFB128 is named in the same sentence as 1 disease in open-access papers, as found by Europe PMC text mining. Sharing a sentence is not in itself a finding about the gene and the disease. The quoted sentences say what the papers report.
Bell's palsy (1 paper, 2025). Partial or complete paralysis of the facial muscles of one side of a person's face. "Our results of the analyses suggest that HMOX2, DEFB128, DDX58 and ITM2A may act as risk factors for Bell’s palsy, but their association with the JAK/STAT signaling pathway is weak." (PMID 40299566, 2025). "In this study, 70 inflammation-related proteins that may be causally associated with Bell’s palsy were identified by MR analysis, and 7 significantly related proteins were screened by external dataset validation, including BLVRB, HMOX2, TNFRSF12A, DEFB128, ITM2A, DDX58 and VEGF-A." (PMID 40299566, 2025).